MTFP1 (mitochondrial fission process 1)
Diseases named in the same sentence as MTFP1 in open-access papers (continued):
Sharing a sentence is not in itself a finding about the gene and the disease.
cancer (continued). "MTFP1 affects calcium homeostasis, lipid metabolism, and signaling by regulating the formation of mitochondria-endoplasmic reticulum contact sites MAMs, which form a complex interaction between cancer cells and the microenvironment." (PMID 41030636, 2025). "Given the multiple roles of MTFP1 in cancer, targeting the function of MTFP1 may provide a new strategy for cancer treatment." (PMID 41030636, 2025). "Targeting the regulatory mechanism of MTFP1 may restore the normal function of mitochondria, reverse metabolic reprogramming, and inhibit the proliferation and survival of cancer cells." (PMID 41030636, 2025). "Strategies targeting MTFP1 may impair the metabolic adaptation of cancer cells by affecting their mitochondrial dynamics and increasing their sensitivity to apoptosis." (PMID 41030636, 2025). "MTFP1 is an integrated IMM egg self that acts on dynein-associated egg-derived cleavage factors upstream of Drp1 and is associated with the activation of mTORC1, cell death, cancer progression, and mitochondrial bioenergetics." (PMID 41030636, 2025). "We show here that mTORC1 accelerates cancer dissemination by directing MTFP1 protein expression." (PMID 35589683, 2022). "Studies have suggested mTORC1 activation contributes to elevated cancer migration, invasion, and metastasis, while mTOR inhibition results in mitochondrial elongation and branching, and the morphology can be completely reversed by overexpressing MTFP1." (PMID 35589683, 2022). "Therapies targeting MTFP1 may enhance the sensitivity of cancer cells to treatment by restoring mitochondrial function (maintain cellular energy production, regulate apoptosis, and balance cellular stress responses) and decreasing the activity of glycolytic metabolism." (PMID 41030636, 2025). "In human cancer cells, ZBTB48 knockout strongly downregulated mitochondrial fission process 1 (MTFP1), mirroring the mitochondrial matrix reorganization phenotype of MTFP1 depletion." (PMID 39987415, 2025). "Current studies have demonstrated that inhibition of MTFP1 can effectively reduce tumor volume and inhibit metastasis, but it also presents an important challenge of how to specifically target MTFP1 dysfunction in cancer cells without damaging normal cells." (PMID 41030636, 2025). "The authors further concluded that uncoupling MTFP1 levels from the TORC1/4E-BP pathway after mTOR inhibition blocks the hyperfusion status and leads to apoptosis, thereby offering a new therapeutic opportunity for these type of anti-cancer drugs, converting them from cytostatic to cytotoxic." (PMID 29466320, 2018).
tumor (6 papers, 2018 to 2025). "Against this backdrop, small-molecule agonists and inhibitors of MTFP1, as well as RNA interference and gene-editing tools, have demonstrated potential in animal studies to improve metabolic disorders and suppress tumor progression." (PMID 41030636, 2025). "In tumor heterogeneity and treatment resistance, the energy regulation mechanism of MTFP1 in tumor cells has been gradually explored." (PMID 41030636, 2025). "In future studies, in-depth exploration of the specific mechanisms of MTFP1 in different tumor types will help to develop more precise and effective treatments." (PMID 41030636, 2025). "The expression level and functional status of MTFP1 were significantly different among different tumor types and subtypes, which directly affected the sensitivity of tumor cells to chemotherapy, radiotherapy and other treatments." (PMID 41030636, 2025). "It has been reported that mitochondrial fission process protein 1 (encoded by MTFP1) is one of the key regulators of mitochondria fission, and involved in cell apoptosis, carcinogenesis, and tumor progression." (PMID 35350385, 2022). "In addition, MTFP1 can also be used as a biomarker to predict treatment response and patient prognosis for different tumor subtypes." (PMID 41030636, 2025). "Our research found that MTFP1 exhibits low expression in tumor tissue." (PMID 40725242, 2025). "Similarly, MTFP1 was expressed at a low level in tumor tissue." (PMID 40725242, 2025).
cardiovascular disease (2 papers, 2022 to 2025). "Its dysfunction has been linked to the development of various cardiovascular diseases, suggesting that MTFP1 may serve as a therapeutic target for the treatment of these diseases." (PMID 41030636, 2025).
heart disease (2 papers, 2021 to 2022). "We propose that MTFP1 to be a valuable tool for the molecular dissection of mitochondrial uncoupling and mPTP function and thus a promising target to mitigate the pathological events of cardiac and metabolic remodeling in heart disease." (PMID 36333300, 2022).
metabolic disease (1 paper, 2025). A congenital disorder (due to inherited enzyme abnormality) or acquired (due to failure of a metabolically important organ) disorder resulting from an abnormal metabolic process. "Studies have shown that the loss of MTFP1 function is closely associated with mitochondrial fragmentation and lipid metabolism dysregulation, thus accelerating the progression of metabolic diseases." (PMID 41030636, 2025). "By targeting the function of MTFP1, mitochondrial homeostasis can be restored and the progression of metabolic diseases can be mitigated." (PMID 41030636, 2025). "Preclinical studies have shown that mitochondrial dynamics can be effectively improved by restoring or improving the function of MTFP1, thereby reversing metabolic disorders." (PMID 41030636, 2025).
neurodegenerative disease (1 paper, 2025). A disorder of the central nervous system characterized by gradual and progressive loss of neural tissue and neurologic function. "Furthermore, MTFP1 exerts a protective role in neurodegenerative diseases by regulating mitochondrial autophagy, which reduces the accumulation of toxic proteins in neurons and delays disease progression." (PMID 41030636, 2025).
MTFP1 also shares sentences with these, for which no sentence is quoted: myocardial infarction (5 papers); diabetes (2); acute kidney injury (1); acute myocardial infarction (1); Adult onset (1); Alzheimer disease (1); cerebrovascular diseases (1); chronic heart failure (1); endometrial cancer (1); endothelial dysfunction (1); Hearing impairment (1); Impaired glucose tolerance (1); infection (1); ischemic stroke (1); liver fibrosis (1); lung carcinoma (1); memory impairment (1); multiple sclerosis (1); myopathies (1); neurological diseases (1); non-alcoholic fatty liver disease (1); osteosarcoma (1); pancreatic cancer (1); Parkinson disease (1); sarcopenia (1); virus infection (1).